CD9 (CD9 molecule)
Diseases named in the same sentence as CD9 in open-access papers (continued):
Sharing a sentence is not in itself a finding about the gene and the disease.
tumor (continued). "Our results confirmed that tumor cells CD9 positive may establish intimate contact with endothelial cells." (PMID 35563166, 2022). "Interestingly, when DEXs are exposed to anti-CD9 antibodies before treatment, they fuse to a lesser extent with tumor cells, indicating this molecule’s role in integrating the exosome with the tumor cell." (PMID 35550636, 2022). "Caution should be taken when targeting CD9 as it may also play a tumor suppressor role in certain cancers and blocking its activity may stimulate cancer progression (reviewed in Ref." (PMID 36010551, 2022). "Changes in tumour cell proliferation may also be related to an effect on mitochondrial function induced by CD9 peptide treatment." (PMID 34012515, 2021). "MCT1+CD9+ EV levels were significantly decreased after tumor resection." (PMID 33920416, 2021). "However, in those circumstances, Evs and tumor cells were incubated together in the presence of anti-CD9 antibodies or their derived Fab portions." (PMID 34451831, 2021). "Accordingly, the internalization of Evs by tumor cells has been recently found to be either impaired by treatment with antigen-binding fragment (Fab) of anti-CD9 antibody or slightly enhanced by incubation with anti-CD9 antibody." (PMID 34451831, 2021). "In most instances, the protein content of CAF-EVs is comparable between different tumor types and includes proteins normally enriched in exosomes such as CD9, CD63 and CD81 and proteins involved in exosome biogenesis like ESCRT-associated proteins, Alix, TSG101, HSC70 and HSP90β." (PMID 33899109, 2021). "In addition, we detected the expression levels of three tumor-specific biomarkers, namely, CD9, MCT1, and cyclin D1, in exosomes." (PMID 34336125, 2021). "It appears that high tetraspanin levels, namely CD82 and CD9, are related to tumor growth inhibition, as studies have demonstrated that in some late-stage tumors, such as colorectal cancer, these tetraspanins are downregulated and therefore associated with poor prognosis." (PMID 34830819, 2021). "Similarly, serum MCT1+CD9+ EVs decreased after neoadjuvant chemotherapy and further decreased after tumor resection." (PMID 33920416, 2021). "In addition, CD9 divided CD11b+cDC2s into two subgroups in B16-F10 tumor-bearing mice, namely CD9–(CD301–)/CD9+(CD301+)CD11b+cDC2s, which are required for activating antitumor CD4+ Tconv." (PMID 33681216, 2021). "Since EVs express tetraspanin family proteins such as CD63, CD81, and CD9, circulating EVs could be monitored by the detection of these proteins and other markers specific to tumor-specific EVs." (PMID 33920416, 2021). "However, whereas the control samples had relatively constant amounts of CD9, the tumor samples varied in abundance." (PMID 34368146, 2021). "In Cases 3 and 4, the serum MCT1+CD9+ EVs decreased after tumor resection." (PMID 33920416, 2021). "In vivo, CD9 peptide delayed primary tumour cell growth and reduced metastasis size." (PMID 34012515, 2021). "It was also demonstrated that the use sof a fragment of CD9-antibody could prevent the transfer of tumor-derived EV cargoes in recipient cells in vitro." (PMID 33670146, 2021). "Indeed, in this study, MCT1+CD9+ was detected in all of the serum samples obtained from patients with localized and metastatic SS, which seemed to accurately reflect the tumor burden." (PMID 33920416, 2021). "Serum levels of MCT1+CD9+ EVs reflected tumor burden and treatment response in SS patients." (PMID 33920416, 2021). "Cells with a phenotype similar to dNK (CD56brightCD16lowCD49+CD9+ decidual-like NK) cells and the nurturing activity of NK cells have been described in cancer, indicating the relevance of NK cells in the development of tumor angiogenesis." (PMID 34944871, 2021). "Furthermore, we identified higher MCT1+CD9+ EV levels in the tumor-bearing group than in the non-tumor bearing group." (PMID 33920416, 2021).
tumor (continued). "There was a non-significant trend towards decreased total tumor weight (p = 0.25), however, Cd9 deletion did impair tumor growth of the largest tumor per mouse, with Cd9−/− mice displaying a significantly lower tumor weight (median 0.96g vs. 1.61g, * p = 0.02)." (PMID 32224917, 2020). "Further ImageStream analysis revealed the expression of epithelial cell adhesion molecule (EpCAM) and exosome specific surface markers, including CD9, CD63, tumor susceptibility gene 101 (TSG-101), and CD81 confirming the tumor cell-derived vesicles as exosomes." (PMID 32456301, 2020). "Only vesicles from one out of two the tumours used for Western blot were positive for CD9." (PMID 32128073, 2020). "The differential association of TSPAN29 (CD9) with CD315, CD316, epithelial cell adhesion molecule (EPCAM), claudin 1 and heparin-binding EGF-like growth factor (HB-EGF) can be related to the different effects on tumor cell invasion and metastasis." (PMID 32138170, 2020). "Moreover, to confirm these findings in vivo, CD9- or CD81-overexpressed Huh7 cells were used to establish a subcutaneous xenotransplanted tumor model in nude mice." (PMID 32350244, 2020). "In oncology, CD9 overexpression in tumors has been associated increased risk of invasion and development of metastasis, especially when it forms a complex with its molecular partner CD81, where it then facilitates long-term tumor growth." (PMID 31191817, 2019). "Interestingly, studies have reported that CD9 and CXCL12 are associated in a CD9/CXCL12/CXCR4 signaling pathway, and activation of this pathway is linked to increased tumor invasion, metastasis, and chemoresistance." (PMID 31191817, 2019). "CD9, as constituent of exosomes, could be a potential target for exosome-mediated tumor development." (PMID 30356731, 2018). "Finally, CD9 is overexpressed in esophageal squamous cell carcinoma tissues and its expression is correlated with tumor stage and lymph node metastasis." (PMID 30356731, 2018). "In addition, we show that compromising release of CD9 + exosomes results in significantly decreased innervation in vivo, further implicating tumor released exosomes as mediating tumor innervation." (PMID 30327461, 2018). "Up-regulation of CD9, especially on the cell surface, has been shown to serve an important role in communication between tumor cells and the microenvironment, allowing trans-endothelial migration and hence metastasis, which opposes the notion that CD9 functions as a generic metastasis suppressor." (PMID 29416746, 2018). "Moreover, they showed that in plasma obtained from a metastatic PCa patient cohort the level of CD9+ EVs were higher in circulating tumor cell (CTC)-positive PCa patients compared with CTC-negative patients." (PMID 29951374, 2018). "Similarly, EV derived from these tumor cell lines expressed TF antigen on immunoblotting, with flotillin and CD9 expression confirming successful isolation of EV." (PMID 29164060, 2017). "Early tumor progression was accompanied by an increase in CD9+/GFAP+/SVN+ exosomes." (PMID 29383115, 2017). "CD9 is considered to be a tumor suppressor and facilitates tumor angiogenesis." (PMID 28977990, 2017). "Multivariate survival analysis was performed in the 476-tumor cohort to determine whether CD9 expression provides additional predictive power over established clinical and molecular prognostic markers." (PMID 27572323, 2016). "By impacting at matrix metalloproteinases, CD9 may regulate not only cell migration but also tissue remodelling during embryonic development, angiogenesis, tumour invasion and metastasis, and also tissue regeneration." (PMID 25890097, 2015). "Expression level and outcome of CD9 activity in human tumors depends on the tumor origin." (PMID 26036626, 2015). "In certain types of carcinoma, CD9 propels tumor progression and metastasis." (PMID 24520284, 2014). "Similarly, blocking of CD26 or CD9 by antibodies inhibited in vitro tumor growth in MSTO-CD26(+) and MESO1 cells." (PMID 24466195, 2014).
tumor (continued). "Such a contradictory phenomenon reflects the complexity of CD9, which may vary with types of tumor and may also depend on different molecules in the tetraspanin web." (PMID 24520284, 2014). "This is why specific tumor cells, expressing higher levels of CD9, are more motile." (PMID 24520284, 2014). "Our co-immunoprecipitation analyses with [3H]-palmitate-labeled tumor cells indicate that a number of proteins, including CD9 and CD81, were no longer associated with α3β1 integrin in the absence of CD151." (PMID 25356755, 2014). "In conclusion, we speculate that specific types of tumor expressing high levels of CD9 destroy the ECM through triggering the activity of MMPs, allowing them to contact with vascular ECs." (PMID 24520284, 2014). "Furthermore, combined treatment with anti-CD26 mAb and anti-CD9 mAb resulted in marked inhibition of tumor growth in vivo." (PMID 24466195, 2014). "In view of previous data suggesting CD9 involvement in suppressing tumor metastasis, CD26 ability to promote tumor cell invasion and migration may be influenced by the anti-metastatic activity of CD9." (PMID 24466195, 2014). "A concept was gradually formed by previous studies that CD9 may selectively hamper several metastasis-promoting processes, including tumor cell motility, epithelial mesenchymal transition and recruitment of a protective environment." (PMID 24520284, 2014). "We next examined the effects of combined blocking of CD26 and CD9 on tumor cell proliferation." (PMID 24466195, 2014). "Collectively, our findings suggest that CD26 potentiates tumor cell invasion through its interaction with α5β1 integrin, and CD9 negatively regulates tumor cell invasion by reducing the level of CD26-α5β1 integrin complex through an inverse correlation between CD9 and CD26 expression." (PMID 24466195, 2014). "Conversely, in specific cases, CD9 may promote tumor progression through the following three aspects: Facilitating tumor cell transmigration, increasing tumor cell motility and hastening the growth of some cancers." (PMID 24520284, 2014). "CD9 is a potential tumor suppressor, while CD151 is supposed to promote tumor metastasis." (PMID 24995331, 2014). "Moreover, combined treatment with anti-CD26 mAb and anti-CD9 mAb resulted in enhanced inhibition of tumor growth in these cell lines." (PMID 24466195, 2014). "Some genes are also related to adaptive immune responses (eg, CD14) and tumor metastasis (eg, CD9)." (PMID 23717493, 2013). "One member of the tetraspanin family, CD9, is particularly important in tumor cell biology." (PMID 23840773, 2013). "Collectively, our studies provide mounting evidence that altered expression of CD9 may be a novel approach to regulate tumor cell progression." (PMID 23840773, 2013). "Future studies should aim to elucidate the mechanism by which PKCα regulates α3β1 function in tumor cells, and the interplay between CD9/CD81, CD151, and other TEM-resident proteins such as the major CD9/CD81 partners, IgSF proteins EWI-2 and EWI-F/CD9P-1, in regulating metastatic cell behaviors." (PMID 23613949, 2013). "It is possible that hypopalmitoylation of both CKAP4 and CD9 may increase tumor or metastatic behavior." (PMID 23457560, 2013). "Our study also shows that this loss of CD9, when associated with the increase in CD9P-1 expression, could be a tumour growth-limiting phenomenon." (PMID 21206492, 2011). "Recently, it was shown that CD9 is highly expressed in hEC, suggesting that an important source of CD9 that was detected within the tumour core could originate from the invading neovessels." (PMID 21206492, 2011). "Perinuclar localisation of mortalin could thus not only define a senescence group, but also identify cells or tumour types that will be sensitive to CD9 overexpression." (PMID 17848953, 2007). "Of the 20 known members, five – MRP1/CD9, ME491/CD63, KAI1/CD82, CD151, CD81 – may be implicated in cell migration, proliferation and tumour cell metastasis." (PMID 14735195, 2004).
tumor (continued). "Reduced MRP-1/CD9 expressions significantly correlated to tumour depth (P = 0.0009)." (PMID 10098753, 1999). "Moreover, CD9 may impact tumor sensitivity to radiation therapy by modulating the metastatic and invasive properties of tumor cells." (PMID 40530955, 2025). "However, in recent years, CD9 has also been found to be involved in tumor progression." (PMID 40860827, 2025). "In the tumor microenvironment, other cell types may contribute to total CD9 EV levels." (PMID 37638157, 2023). "In addition to proliferation and exosome function in tumor cells, CD9 is also broadly expressed by different immune cell types with an important role in shaping both anti-tumor immunity and pro-tumor immunity depending on the different types of immune cells present in the tumor niche." (PMID 37542044, 2023). "As highlighted in the review, CD9 is not unequivocally associated with either tumor suppression or promotion, and the antibodies used to detect CD9 might be problematic." (PMID 37007105, 2023). "Therefore, different molecules on the EV surface (including ALCAM and ADAM17) are involved in the interactions between tumor-derived EVs and recipient cells and the adhesive capacity of these molecules may be subjected to additional regulation by EV CD9." (PMID 35628559, 2022). "Although we cannot completely rule out an effect on the competence of the metastatic niches formed by EVs secreted by cells treated with CD9 peptide, our data suggest that the major effect on tumour progression in this case could be attributed to an impairment in tumour cell proliferation." (PMID 34012515, 2021). "CD9 is also important for the bone metastasis since it was reported that CD9 was significantly overexpressed in bone metastases versus primary tumors and visceral metastatic lesions, and that its inhibition delays homing of tumor cells in bone marrow, slowing down bone destruction." (PMID 34830463, 2021). "Furthermore, serum levels of MCT1+CD9+ EVs reflected tumor burden in SS patients." (PMID 33920416, 2021). "Additionally, due to its presence in the lymphatic vessels, CD9 may also be involved in tumor–endothelial cell interaction and therefore contribute to tumor lymphangiogenesis." (PMID 34830819, 2021). "Consequently, we propose that whether CD9 increases the motility or invasion of tumor cells depends on the prevailing conditions, particularly the partner proteins associating with CD9." (PMID 24520284, 2014). "In addition, CD9 appears to be an important marker of cancer stem cells in certain types of tumor." (PMID 24520284, 2014). "Similarly, anti-CD26 mAb or anti-CD9 mAb inhibited tumor growth in vivo." (PMID 24466195, 2014). "Furthermore, combined depletion of both CD26 and CD9 effectively inhibited in vitro tumor growth." (PMID 24466195, 2014). "Therefore, CD9 consequently may play an important role in tumor cell invasion and promoting metastasis." (PMID 23840773, 2013). "However, in tumours of GS-168AT2-treated animals, only trace amounts of CD9 were detected." (PMID 21206492, 2011). "Incubation of GS-168AT2 with the hLT cell line NCI-H460 leads to the association of GS-168AT2 with both CD9 and CD81, and treatment of NCI-H460-xenografted Nude mice with GS-168AT2 leads to a drastic inhibition of tumour growth, which is associated with the in vivo downregulation of CD9 in tumours." (PMID 21206492, 2011). "Our study also reveals that, under certain conditions, loss of CD9 could be a tumour growth-limiting phenomenon rather than a tumour growth-promoting one." (PMID 21206492, 2011). "Finally, CD9 has been shown to interfere with Aggrus-mediated platelet aggregation, which may prevent tumor spread by subjecting metastatic cells to a less protective environment." (PMID 19922654, 2009).
tumor (continued). "Intriguingly, loss of CD9 expression correlates with metastasis and, as reported at the symposium, a strict co-localisation of CD9 and EpCAM, as seen for membranes of normal colonic epithelium, was no longer found for tumour cell membranes." (PMID 17211480, 2007). "In vivo in orthotopic tumors formed by FC1199 cells GAL decreased CD9+-NK frequency, promoted M1-macrophage polarization, and activated NK and CD8+T-cells, together with a significant reduction of tumor weight, fibrosis and inhibition of angiogenesis." (PMID 41916960, 2026). "The expression levels of CD9 and TSG101 proteins were significantly present in the serum of tumor patients and healthy subjects." (PMID 40636359, 2025). "Notably, CD9 exhibited differential expression in tumor-associated macrophages (TAMs), and CellChat-predicted enhanced TGF-β signaling suggests its role in modulating tumor-immune crosstalk, warranting validation via spatial transcriptomics or multiplex immunofluorescence." (PMID 40406701, 2025). "The cell adhesion molecule binding cluster in TuNEPs contained tumorigenic proteins such as ITGA2, CD151, CD9, SLC3A2, and BSG, all known to have an impact on the tumor microenvironment." (PMID 40751052, 2025). "The violin diagram shows that in HNSCC tissue, macrophages highly expressed four classic marker genes (CD63, CD9, CD81, TSG101) of exosomes, suggesting that TAM-EVs are highly secreted in the tumor microenvironment." (PMID 38602536, 2024). "MiR‐31 represses tumour suppressors DACH1 and CEBPA, which otherwise direct the CD9, CD82 and AXIN1 expression." (PMID 38797942, 2024). "CD9, CD151, TSPAN1, TSPAN3, TSPAN8, and TSPAN13 displayed specific overexpression in the tumor compartment, indicating potential roles in tumor growth." (PMID 38255741, 2024). "The literature reports also demonstrate that TBX3 upregulates important gene targets involved in tumor development, angiogenesis and ion transport such as versican (VCAN), CD9, chromo-domain helicase DNA binding protein 1 (CHDR1) and CD86." (PMID 39358558, 2024). "In the tumor compartment, several tetraspanins (CD9, CD151, TSPAN1, TSPAN3, TSPAN8, and TSPAN13) were specifically overexpressed, suggesting their involvement in tumor growth and proliferation in stage 4 primary CC." (PMID 38255741, 2024). "Cathepsin B cleavage site introduced between CD9/CD81 and RFP was recognized by tumor specific proteases allowing the release of the reporter protein." (PMID 36579638, 2023). "CB2 stimulation reduces the expression of CD9, SEC61G, TBX21, and TMSB4X genes involved in tumor growth and progression, and also negatively affects downstream intracellular pathways." (PMID 35955786, 2022). "In particular, in ALL patients they observe a CD9-mediated overexpression of the RAC1 protein, an important mediator of cell migration and tumor progression." (PMID 35955786, 2022). "CD9 (Tspan4) and CD81 (Tspan28), depending on tumor type, can promote or suppress disease progression, while some other Tspan proteins, such as CD82 (Tspan27) and CD63 (Tspan30), have solely been established as tumor suppressors." (PMID 36143328, 2022). "In addition, to be potential candidates for cancer biomarkers, a recent study using immunohistochemistry (IHC) showed that tumor exosomal CD9 and CD63 might also act as potential prognostic monitors due to the increased expression in rectal tumor tissue after chemoradiation treatment." (PMID 35757760, 2022). "The mean tumor CD63 and CD9 scores respectively in post-NCCR resected rectum was 155 and 205 in patients with low-intermediate NAR score compared to 180 and 230 in patients with high NAR score (P = 0.3793) (P = 0.2837)." (PMID 34316329, 2021). "Both of the two tumor cell-derived exosomes showed positive expression of exosome markers, including HSP70, CD63, and CD9." (PMID 33644057, 2021).